WNT4 (Wnt family member 4)
Diseases named in the same sentence as WNT4 in open-access papers (continued):
Sharing a sentence is not in itself a finding about the gene and the disease.
atherosclerosis (4 papers, 2021 to 2025). A disease characterized by the build-up of fatty material and calcium deposition in the arterial wall resulting in partial or complete occlusion of the arterial lumen. "MiR-145 was positively correlated with WNT4, with a decrease in the expression of which the progression of atherosclerosis has been proven according to literature data." (PMID 38139440, 2023). "Furthermore, we elucidated the role of TEAD1 in regulating the trans‐differentiation of VSMCs into fibroblast‐like cells via the Wnt4/β‐Catenin signaling pathway, which promoted plaque repair during the dynamic process of atherosclerosis." (PMID 39665254, 2025). "In addition, it is known that there is a close correlation between the WNT4 protein level and the development of stenosing atherosclerosis." (PMID 38139440, 2023). "Thus, we concluded that WNT4 mediates the role of circUSP36 in an in vitro cell model of atherosclerosis." (PMID 34519627, 2021). "Lastly, we investigated whether circUSP36 acts as a regulator of atherosclerosis by targeting miR-637-mediated WNT4." (PMID 34519627, 2021). "In conclusion, circUSP36 regulated WNT4 to aggravate endothelial cell injury caused by ox-LDL by competitively binding to miR-637; this finding indicates circUSP36 to be a promising biomarker for the diagnosis and therapy of atherosclerosis." (PMID 34519627, 2021). "Additionally, knockdown of WNT4 offset the role of circUSP36 in ox-LDL-treated endothelial dysfunction in atherosclerosis." (PMID 34519627, 2021). "The upregulation of WNT4 has been reported to be strongly related to vascular stenosis, and WNT4 might represent a therapeutic target for the prevention of vascular restenosis in atherosclerosis." (PMID 34519627, 2021).
breast tumors (4 papers, 2016 to 2022). "Given that WNT4 upregulation activates WNT signaling, this suggests that activated WNT signaling potentially mediates the effect of WNT4 on promoting BCSC generation in BRCA1-deficient breast tumors." (PMID 27556296, 2016). "We used public datasets from The Cancer Genome Atlas and the METABRIC study to assess WNT4 expression and associations with clinical and molecular features in breast tumors." (PMID 27650553, 2016). "The authors also found that NEAT1 increased the malignant biological behaviors of BRCA1- knockdown breast neoplasm cells through suppressing mir-129-5p and subsequently enhancing the expression of oncogene WNT4." (PMID 28118609, 2017). "Across ER-positive breast tumors, WNT4 expression was higher in ILC than in IDC, but this may be due to the increased proportion of luminal A tumors among ILCs." (PMID 27650553, 2016). "Importantly, the expression data currently available represent static, pretreatment measurement of WNT4 expression in breast tumors; regulation of WNT4 expression following endocrine therapy may be a superior biomarker for ILC biology." (PMID 27650553, 2016). "In contrast to normal human epithelial cells, HR‐positive breast tumors proliferate via autocrine mechanisms that involve PR‐induced expression of RANKL, Wnt4, and cyclin D1, as well as PR‐induced activation of protein kinases including CDK2, c‐Src, CK2, MAPK, and PI3K/AKT." (PMID 34714554, 2022).
Hypertension (4 papers, 2017 to 2024). The presence of chronic increased pressure in the systemic arterial system. "miR-634 inhibits human vascular smooth muscle cell proliferation and migration in hypertension through the Wnt4/β-catenin pathway." (PMID 38704809, 2024). "Moreover, urinary Wnt4 may be a noninvasive biomarker for monitoring renal injury after hypertension." (PMID 28383024, 2017).
Obesity (4 papers, 2014 to 2023). Accumulation of substantial excess body fat. "Since previous studies have implicated WNT5A and WNT4 in adipogenesis, we hypothesized that WNT5A and WNT4 might influence obesity related traits and might be candidate susceptibility genes for obesity." (PMID 28272483, 2017). "Together with previous reports of WNT4 up-regulation in obesity our observations suggest an adaptive insulin response coordinating β-cells." (PMID 36271049, 2022). "The expression of Wnt4 and Tnfs11 are critical for normal progesterone mediated mammary gland development and in response to obesity, Sfrp1−/− mice express significantly more Wnt4 and Tnfs11 mRNA expression." (PMID 24885183, 2014). "However, the associations of WNT4 polymorphisms with obesity related traits in subjects without special medical problems are still unknown." (PMID 28272483, 2017). "The pancreata of rats with diet-induced obesity showed a high expression of Pdx1 (P<0.05) together with low transcript levels of Wnt4 (P<0.05), without changes in Neurog3." (PMID 37274331, 2023). "Considering the biological roles of WNT4 and WNT5A involved in adipogenesis, we aimed to investigate whether SNPs in WNT4 and WNT5A contribute to obesity related traits in Han Chinese population." (PMID 28272483, 2017).
ovarian tumors (4 papers, 2013 to 2023). "In pathological conditions such as uterine leiomyomas, ovarian tumors, and cervical cancer, WNT4 gene expression is altered compared to histologically benign tissues." (PMID 37835474, 2023). "For WNT4, reduced expression in ovarian tumour cells compared to normal ovarian tissue has been observed in one study, which agrees with our own data showing weak expression of WNT4 in omTU." (PMID 34841720, 2021). "Indeed, data from a large genome-wide association study (GWAS) in EOC were indicative for a significant downregulation of the Wnt pathways-agonist WNT4 in ovarian tumors." (PMID 32679765, 2020).
acute kidney injury (3 papers, 2011 to 2021). Sudden and sustained deterioration of the kidney function characterized by decreased glomerular filtration rate, increased serum creatinine or oliguria. "Complete failure to produce nephrons results in renal agenesis and postnatal death due to renal failure — as seen in mice with homozygous loss of Wnt4." (PMID 21295565, 2011). "WNT4 was found to be significantly upregulated during the early phase of cisplatin-induced acute kidney injury (AKI) and following ischemia–reperfusion injury in mice." (PMID 34642299, 2021). "Our previous studies identified that renal and urinary Wnt4 are upregulated following ischemia-reperfusion injury in mice, but the roles of Wnt4 in other forms of acute kidney injury (AKI) remain unclear." (PMID 30002385, 2018). "Wnt4−/− mice are thus born without nephrons and consequently die of renal failure." (PMID 21295565, 2011).
basal cell carcinoma (3 papers, 2009 to 2025). A carcinoma involving the basal cells. "Interestingly, Wnt4 has been identified as a target gene of Shh signalling in basal cell carcinomas whose mRNA levels are downregulated compared to normal skin." (PMID 19732418, 2009).
dwarfism (3 papers, 2007 to 2021). "Most relevant, conditional expression of Wnt4 in mice also causes dwarfism with small skeletons, dome-shaped skulls, and small jaws." (PMID 34595172, 2021). "We found that Wnt4 expression in chondrogenic tissues alters skeletogenesis, resulting in skull abnormalities and dwarfism." (PMID 17505543, 2007). "It is not clear which pathway(s) is utilized for the Wnt4-induced dwarfism documented in our study." (PMID 17505543, 2007).
female infertility (3 papers, 2017 to 2025). Diminished or absent ability of a female to achieve conception. "We also identified an intronic variant in WNT4, rs61768001, associated with three categories of female infertility (F-ALL=0.909 (0.891–0.927), F-EXCL=0.923 (0.902–0.946), F-INCL=0.870 (0.839–0.903))." (PMID 38562841, 2024). "We also identified an intronic variant in WNT4, rs61768001 (MAF of 16.5%), associated with three categories of female infertility (F-ALL, OR 1.10 (1.08–1.12); F-EXCL, OR 1.08 (1.06–1.11); F-INCL, OR 1.15 (1.11–1.19))." (PMID 40229599, 2025). "Wnt4 may be involved in the pathogenesis of female infertility; spermatozoon-derived Wnt4 is transported to the fertilized egg and translated, and this process may be important in early embryonic development and provide a basis for the paternal gene effect." (PMID 28599310, 2017).
glioma (3 papers, 2014 to 2019). A benign or malignant brain and spinal cord tumor that arises from glial cells (astrocytes, oligodendrocytes, ependymal cells). "Inhibition of Wnt3a, but not Wnt4 or Wnt5a, attenuated cell growth and neural sphere formation in these PN glioma spheres." (PMID 27698350, 2016).
hepatocellular carcinoma (3 papers, 2021 to 2025). A malignant tumor that arises from hepatocytes. "These compounds can also disrupt the hepatoprotective effects of the Wnt4/β-linker pathway, potentially extending the survival of rats with hepatocellular carcinoma." (PMID 39940837, 2025). "At present, limited studies on PIK3CD, HRAS, E2F2, BIGF1, WNT4, and VAV3 genes have been reported in hepatoma cells, indicating the need for further research." (PMID 33959508, 2021).
hyperandrogenemia (3 papers, 2014 to 2024). "In a group of patients with hyperandrogenemia, variants of WNT4 are causative." (PMID 38812815, 2024).
leukemia (3 papers, 2008 to 2022). A malignant (clonal) hematologic disorder, involving hematopoietic stem cells and characterized by the presence of primitive or atypical myeloid or lymphoid cells in the bone marrow and the blood. "We showed that WNT4 expression is strongly reduced in leukemia-derived cell lines and in blasts from patients with leukemia compared with the expression in mature blood cells from healthy individuals." (PMID 24274766, 2013). "Our results show that WNT4 is expressed in normal cells, predominantly in B-cells, but that its expression is strongly reduced in leukemia-derived cell lines and in BM cells from patients with leukemia." (PMID 24274766, 2013). "In summary, leukemia-derived cell lines and bone marrow cells from patients with leukemia show a statistically significant decrease in the expression of WNT4 when compared with the expression in PBMCs from healthy individuals." (PMID 24274766, 2013). "WNT4 expression was severely reduced in leukemia-derived cell lines and blasts derived from patients with leukemia." (PMID 24274766, 2013). "To corroborate the effect observed on cell viability by the addition of rhWNT4 to leukemia-derived cell lines, we decided to restore WNT4 expression in leukemia-derived cells." (PMID 24274766, 2013). "We obtained complementary DNA (cDNA) from the leukemia-derived cells and the healthy PBMCs, and determined expression of WNT4 by quantitative Reverse transcriptase-Polymerase chain reaction (qRT-PCR) in all samples." (PMID 24274766, 2013). "We report here that WNT4 cell-growth inhibition in leukemia-derived cells appears to be FZD6-independent, at least in myeloid cell lines (K562 and HL60), because this receptor is not expressed in these cells at the protein level." (PMID 24274766, 2013). "POL and SRG performed flow cytometry sorting; ARM recruited patients with leukemia and measured WNT4 expression in their cells." (PMID 24274766, 2013). "To corroborate our observations, we analyzed WNT4 protein levels by western blot analysis in the leukemia-derived cell lines, and included protein obtained from two healthy individuals (PBMC1 and PBMC2) as controls." (PMID 24274766, 2013). "Taken together, these results show that WNT4 expression in leukemia-derived cell lines is significantly decreased when compared with that of mature immune-system cells from clinically healthy individuals." (PMID 24274766, 2013). "Our results suggest that WNT4 could act as a tumor suppressor for leukemia by antagonizing WNT/β-catenin signaling." (PMID 24274766, 2013). "Because we showed that WNT4 was more highly expressed in mature lymphocytes derived from healthy volunteers, and that its expression decreased in immature leukemia-derived cells, it was in our interest to determine the biological effects of WNT4 in leukemia-derived cells." (PMID 24274766, 2013). "After demonstrating that WNT4 expression is strongly reduced in leukemia-derived cell lines, we wanted to determine whether WNT4 expression is also reduced in the bone marrow (BM) samples of patients with leukemia." (PMID 24274766, 2013). "Interestingly, of the 11 BM cells from the patients with leukemia included in the study, ten showed very low expression of WNT4; this trend became more strongly evident when compared with the control CD19+ cells." (PMID 24274766, 2013). "We determined WNT4 expression by quantitative reverse transcriptase-polymerase chain reaction (qRT-PCR) in peripheral blood mononuclear cells (PBMCs) and T- and B-lymphocytes from healthy individuals, as well as from five leukemia-derived cell lines and blasts derived from patients with leukemia." (PMID 24274766, 2013). "Because WNT4 is expressed mainly in mature B cells, we thought that the best candidates to analyze the effect of WNT4 restoration would be the BJAB cells, the only leukemia model cell line in our experiments that were CD19+." (PMID 24274766, 2013).
leukemia (continued). "Specifically, in leukemia there is experimental evidence demonstrating the influence of WNT pathway components on the oncogenic growth of disease from both myeloid and lymphoid origin, but there is a very limited number of publications on WNT4 expression and its role in the biology of these cells." (PMID 24274766, 2013).
lymphoma (3 papers, 2007 to 2022). A malignant (clonal) proliferation of B- lymphocytes or T- lymphocytes which involves the lymph nodes, bone marrow and/or extranodal sites. "For example, a BA-deletion in a malignant lymphoma sample was associated with a 37-fold increase in the expression level of WNT4 compared with the rest of samples from patients with lymphoma." (PMID 32024999, 2020). "For example, WNT4 expression was 37-fold increased in a malignant lymphoma with deletion of nearby TAD boundary compared with lymphomas without such deletion." (PMID 36468037, 2022).
male infertility (3 papers, 2012 to 2021). The inability of the male to effect fertilization of an ovum after a specified period of unprotected intercourse. "The identification of WNT4 as a negative regulator of SSC activity may provide insight into the pathogenesis of male infertility." (PMID 22253774, 2012).
myocardial infarction (3 papers, 2022 to 2025). Gross necrosis of the myocardium, as a result of interruption of the blood supply to the area, as in coronary thrombosis. "When focusing on the early post-myocardial infarction (MI) phase, quantitative analyses of Wnt protein expression have unveiled notable upregulation of Wnt-2, Wnt-4, Wnt-10b, and Wnt-11 five days after MI." (PMID 38139379, 2023). "Indeed, Analysis of the expression of Wnt proteins indicated that Wnt-2, Wnt-4, Wnt-10b, and Wnt-11 were significantly upregulated 5 days after myocardial infarction." (PMID 36072583, 2022).
acute lymphoblastic leukemia (2 papers, 2013 to 2020). Leukemia with an acute onset, characterized by the presence of lymphoblasts in the bone marrow and the peripheral blood. "Other Wnts such as Wnt4, Wnt5B, Wnt6, Wnt7B, Wnt9A, Wnt10A, Wnt14, and Wnt16 are robustly expressed in CLL B-cells and acute lymphoblastic leukemia (ALL) cells, whereas these can be scarcely detected in normal pre-B cells." (PMID 33126517, 2020).
androgen insensitivity syndrome (2 papers, 2007 to 2026). Androgen insensitivity syndrome (AIS) is a disorder of sex development (DSD) characterized by the presence of female external genitalia, ambiguous genitalia or variable defects in virilization in a 46,XY individual with absent or partial responsiveness to age-appropriate levels of androgens. "Key conditions to consider include congenital absence of the uterus and vagina (aplasia or agenesis), isolated vaginal atresia, androgen insensitivity syndrome (AIS), and WNT4 gene defects." (PMID 41515635, 2026).
cervical cancer (2 papers, 2019 to 2023). A primary or metastatic malignant neoplasm involving the cervix. "The better rescue effects observed upon ectopic expression of both WNT4 and JIP2 strongly suggested that the WNT4/JIP2 pathway mediated the effect of E6 on promoting cervical cancer cell proliferation." (PMID 31637011, 2019). "By increasing the translation of WNT4 and JIP2, E6 can activate the WNT4-induced noncanonical pathway, and JIP2 facilitates the activation of JNK downstream to promote the proliferation of cervical cancer cells and tumor growth." (PMID 31637011, 2019).
chronic lymphocytic leukaemia (2 papers, 2013 to 2021). "Wnt members, including Wnt3, Wnt4, Wnt5B, Wnt6, Wnt7B, Wnt9A, Wnt10A, Wnt14 and Wnt16, are highly expressed in chronic lymphocytic leukaemia B cells." (PMID 33417298, 2021).
clear cell renal carcinoma (2 papers, 2020 to 2021). A malignant epithelial neoplasm of the kidney characterized by the presence of lipid-containing clear cells within a vascular network. "This study included 185 patients with clear cell renal carcinoma (ccRCC) in whom immunohistochemical expression of Wnt-4 protein in healthy and tumorous tissue after surgery was investigated." (PMID 34945091, 2021). "Renal clear cell carcinoma (RCC; total n = 515, WNT4-high n = 89), lung adenocarcinoma (LuA; total n = 533, WNT4-high n = 57), and serous ovarian cancer (OvCa; total n = 307, WNT4-high n = 39) presented differences in protein signaling by RPPA in WNT4-high tumors." (PMID 33053661, 2020).
colorectal tumor (2 papers, 2020 to 2024). "Our data then substantiated the effects of secretory WNT4 on the development of the colorectal tumor microenvironment." (PMID 33222684, 2020).
focal segmental glomerulosclerosis (2 papers, 2022 to 2026). A renal disorder characterized by sclerotic lesions in the glomeruli. "In kidneys affected by congenital nephrotic syndrome of the Finnish type (CNF) and focal segmental glomerulosclerosis (FSGS), WNT4 decreased in both cell populations, whereas Notch2 decreased in FSGS." (PMID 35886848, 2022).
Insulin resistance (2 papers, 2016 to 2023). Increased resistance towards insulin, that is, diminished effectiveness of insulin in reducing blood glucose levels. "The present data suggest that WNT3a and WNT4 are important components of crosstalk between insulin-resistant tissues and the pancreas in maintaining β-cell adaptation to systemic insulin resistance." (PMID 27527335, 2016). "Notably, in T2D and chronic insulin resistance, we observed Wnt3a downregulation and Wnt4 upregulation in both skeletal muscle and WAT." (PMID 27527335, 2016). "Thus, the higher Wnt3a expression and simultaneous downregulation of Wnt4, as reported herein, appear to be involved in the compensatory mechanism of lipid-induced insulin resistance in skeletal muscle and WAT." (PMID 27527335, 2016). "Here, we show that two Wnt proteins, WNT3a and WNT4, are specifically secreted by skeletal muscle and adipose tissue during the development of insulin resistance and play an important role in cross-talk between insulin-resistant tissues and pancreatic beta cells." (PMID 27527335, 2016). "The present study found that two Wnt proteins, WNT3a and WNT4, are specifically secreted by skeletal muscle and WAT during the development of insulin resistance and play an important role in crosstalk between insulin-resistant tissues and pancreatic β-cells." (PMID 27527335, 2016).
lung adenocarcinoma (2 papers, 2019 to 2020). A carcinoma that arises from the lung and is characterized by the presence of malignant glandular epithelial cells. "During the pulmonary aging process Wnt4 and Wnt5a were identified as inhibitors of lipid uptake and therefore surfactant production, while Wnt7a triggered differentiation and reduced proliferation of lung adenocarcinoma cell lines, respectively." (PMID 31492143, 2019).
nasopharyngeal carcinoma (2 papers, 2008 to 2024). A carcinoma arising from the nasopharyngeal epithelium. "Three hub genes (EME1, WNT4, SHISA2) show strong correlation with m6A regulators and elevated levels of methylation modifications in nasopharyngeal carcinoma tissues." (PMID 39726587, 2024).